INS (insulin)
Diseases named in the same sentence as INS in open-access papers (continued):
Sharing a sentence is not in itself a finding about the gene and the disease.
Glucose intolerance (continued). "But we believe that IR, insulin sensitivity and β-cell function are complementary in the development of acromegalic glucose intolerance, and collectively contribute to the glucose metabolism alterations." (PMID 31736874, 2019). "Starting from 12–13 weeks of age, male CAR−/− mice presented glucose intolerance and decreased insulin sensitivity, as compared to WT." (PMID 31882815, 2019). "Geriatric monkeys exhibited glucose intolerance with impaired glucose‐stimulated insulin secretion following IVGTT." (PMID 30357856, 2019). "Even though CD36-depleted DR rats became as obese as DIO AAV controls, only DIO CD36 depleted rats became insulin-resistant on a 45% HFD as shown by a glucose intolerance and by elevated insulin levels during the oral glucose tolerance test." (PMID 31474875, 2019). "ß cell-specific Pdia1 deletion in young high-fat diet fed mice or aged mice exacerbated glucose intolerance with inadequate insulinemia and increased the proinsulin/insulin ratio in both serum and islets compared to wildtype mice." (PMID 31184304, 2019). "As can be expected, we show that women with GDM who developed glucose intolerance in early postpartum were more insulin resistant and had an impaired beta-cell function compared to NGT women after delivery." (PMID 30893935, 2019). "Earlier experiment studies in mice showed that urea was associated with impaired beta cell function, elevated levels of reactive oxygen species production, reduced insulin sensitivity and glucose intolerance." (PMID 30833930, 2019). "IA-2 beta (−/−) knockout mice show mild glucose intolerance and impaired glucose-stimulated insulin secretion." (PMID 30890718, 2019). "Plasma chemerin levels were found to be increased in diet-induced obese mice, and in another study of obese diabetic db/db mice, the chemerin was found to exacerbate glucose intolerance, lower serum insulin levels, and decrease tissue glucose uptake." (PMID 31736870, 2019). "In all cases, glucose tolerance and insulin sensitivity were enhanced in those who exercised, and indeed the older masters athletes appeared to have successfully overcome the age-related glucose intolerance and deterioration in insulin sensitivity." (PMID 30730811, 2019). "Subsequently, growing numbers of clinical research and animal models confirmed the benefits of genistein on glucose intolerance, insulin sensitivity and lipid metabolic disorders." (PMID 31417434, 2019). "Though still only preliminary, the reports emerging so far suggest an “early” pattern of glucose intolerance, insulin resistance, catabolite accumulation, and altered amino acid metabolism in IUGR neonates." (PMID 31698738, 2019). "Our data suggest that although GH excess reduces insulin sensitivity it is the impaired insulin secretion that drives glucose intolerance." (PMID 31620090, 2019). "Oral glucose tolerance tests showed glucose intolerance and decreased insulin secretion in response to glucose loading in affected males, features which were exacerbated with age." (PMID 31467929, 2019). "To investigate the mechanism of this glucose intolerance, we analyzed the insulin secretion of the mice in response to glucose stimulation." (PMID 31208980, 2019). "Taken together, our results suggested that the sedentary SMA mice exhibit an abnormal glucose homeostasis, which seems largely insulin independent, and whose glucose intolerance was limited by both exercise protocols through a potentiation of insulin response." (PMID 31632295, 2019). "The increase in WAT fat pads observed in this model contributes to the establishment of IR and glucose intolerance in these animals, due to the alteration in the secretion of adipokines leading to the damage in the insulin signaling pathway." (PMID 31022246, 2019). "When examined on days 16–18 of pregnancy, females exposed to BPA revealed glucose intolerance and elevated levels of plasma insulin, triglycerides, and leptin relative to controls." (PMID 30787907, 2019).
Glucose intolerance (continued). "The data are mixed in animal models of iAs-induced metabolic dysfunction regarding the relative contributions of insulin-secretory vs. insulin-sensitivity factors in the development of glucose intolerance." (PMID 31258514, 2019). "Elevated pEphA3 levels block insulin secretion acutely thus leading to defective insulin secretion and glucose intolerance." (PMID 31831727, 2019). "Here we identify arginase 2 (Arg2) as a fasting-induced hepatocyte factor that protects against hepatic and peripheral fat accumulation, hepatic inflammatory responses, and insulin and glucose intolerance in obese murine models." (PMID 30962478, 2019). "TMSC injection successfully normalized HFD-induced glucose intolerance and pancreatic insulin secretion." (PMID 31018536, 2019). "In adult exposure models, male mice exposed to BPA in the context of a high fat diet exhibited glucose intolerance with concordant impairments in skeletal muscle insulin signaling." (PMID 30778334, 2019). "In T2D there is a normal production of insulin from pancreatic β-cells; however, peripheral tissues show resistance to the insulin-mediated action resulting in pathological glucose intolerance." (PMID 31540445, 2019). "It is noteworthy that, in this same study, the authors also showed that these patients have decreased HOMA-β, indicating lower insulin secretion capacity, justifying a higher percentage of patients with glucose intolerance when compared to the control group." (PMID 31939483, 2019). "Previous studies demonstrated that helminth infection and helminth-derived products provide a beneficial impact on insulin sensitivity and glucose intolerance." (PMID 31736971, 2019). "The decreased insulin secretion and the enhanced insulin-resistant state disturb the maternal insulin balance then trigger the maternal glucose intolerance and promote the pathogenesis of GDM." (PMID 31558153, 2019). "As expected, BE-treated mice showed profoundly improved glucose intolerance and insulin sensitivity." (PMID 31472342, 2019). "Instead, it is much more plausible that indirect and paracrine functions of TMSCs were responsible for the observed improvements in HFD-induced glucose intolerance and insulin secretion." (PMID 31018536, 2019). "During an IVGTT, tmx-βACC1KO mice showed glucose intolerance with defective insulin secretion at baseline and in response to glucose stimulation." (PMID 30334081, 2019). "Targeted knock out of the osteocalcin gene (Ocn−/−) in mice resulted in the development of glucose intolerance and a decrease in the number of pancreatic beta cells, while OC favored β-cell proliferation, insulin secretion, and sensitivity through adiponectin." (PMID 30866902, 2019). "Genetic ablation of OcaB resulted in the abrogation of this phenotype, with improvement of glucose intolerance and insulin sensitivity, and reduced fat accumulation during aging due to increased energy expenditure." (PMID 31922096, 2019). "Replenishment of OcaB-/- mice with OcaB+/+ B cells, via bone marrow transfer, was sufficient to re-induce body weight gain, glucose intolerance and insulin insensitivity." (PMID 31922096, 2019). "For acromegaly patients with glucose intolerance that is mostly diagnosed upon admission to the hospital, oral hypoglycaemic agents or insulin should be used before surgery and should be adjusted as needed while closely monitoring the blood glucose." (PMID 31736874, 2019). "Consumption of high‐fat diet can result in impaired pancreatic function of insulin secretion, leading to glucose intolerance." (PMID 31024702, 2019). "Consistent with the observed glucose intolerance, the response of the blood glucose concentration to an IP injection of insulin was also impaired." (PMID 31399502, 2019). "Although normal fasting plasma glycaemia is observed in glucose intolerance, the postprandial blood glucose and the corresponding insulin response are elevated in this period." (PMID 30166558, 2018).
Glucose intolerance (continued). "β cell-specific Sirt6-ko mice are glucose intolerance and are defective in glucose-stimulated insulin secretion, in spite do not show abnormality in endocrine morphology, pancreatic β cell mass or insulin production." (PMID 30574122, 2018). "Inflammation, specifically due to cytokines and chemokines produced by FFA and gut-derived LPS activation of TLR4 signaling, leads to systemic glucose intolerance by impairing insulin signaling in target tissues including adipose and liver." (PMID 29666152, 2018). "Mutations in HNF1α are responsible for the commonest type of monogenic diabetes (MODY3), characterised by progressive glucose intolerance due to an insulin secretory defect." (PMID 29764441, 2018). "It was further determined that HFD feeding resulted in glucose intolerance and peripheral insulin sensitivity." (PMID 30619085, 2018). "The glucose intolerance in GK rat is mainly attributed to the impairment in glucose-stimulated insulin secretion (GSIS)." (PMID 30687391, 2018). "al findings, insulin sensitivity in obese women with lower glucose intolerance is lower than women with normal weight and insulin sensitivity in pregnant women with gestational diabetes decreases with increasing gestational age." (PMID 30820209, 2018). "This glucose intolerance is likely attributed to reduced insulin sensitivity, as these mice also required a lower GIR to maintain blood glucose during the hyperinsulinaemic–euglycaemic clamp." (PMID 30043179, 2018). "Knockdown of hepatic Gomafu resulted in decreased gluconeogenesis and increased insulin sensitivity, subsequently improving glucose intolerance in high-fat diet mice and ob/ob mice." (PMID 29459686, 2018). "Taken together, most studies suggest that ATX-LPA-LPA1/3 signaling promotes glucose intolerance and impairs systemic insulin sensitivity and tissue insulin signaling." (PMID 29570618, 2018). "While rapamycin-mediated glucose intolerance was unaffected by metformin in males, we found metformin prevented rapamycin-mediated reduction in insulin and leptin concentrations following 9 months of co-treatment." (PMID 29579736, 2018). "On the other hand, the ablation of HGF/c-Met signaling, in adult murine β-cells, led to a decrease in GLUT-2 expression, followed by glucose intolerance and an impairment in glucose-stimulated insulin secretion." (PMID 30214428, 2018). "Although the relationship between changes of insulin clearance and the progression of glucose intolerance have been reported, the effects of insulin clearance are controversial." (PMID 29560274, 2018). "Due to a close association between hepatosteatosis and systemic insulin resistance, we observed a glucose intolerance and reduced insulin sensitivity in mice overexpressing USP14, as revealed by glucose and insulin tolerance tests." (PMID 30425250, 2018). "Consistently, heterozygous and homozygous Gpr1-knockout mice fed with high-fat diet develop severe glucose intolerance but exhibit reduced glucose-stimulated insulin level." (PMID 29848608, 2018). "Impairment in hepatic insulin signaling results in glucose intolerance, lipid synthesis and chronic IR." (PMID 30572687, 2018). "β-cell-specific Pin1 KO (βPin1 KO) mice developed glucose intolerance owing to reduced insulin secretion but preserved peripheral insulin sensitivity." (PMID 30096758, 2018). "Monoamines act as insulin inhibitors and produce a mild condition of intermediate glucose intolerance." (PMID 29805204, 2018). "HFD consumption is known to induce alteration in insulin sensitivity leading to glucose intolerance and a state of prediabetes." (PMID 29768504, 2018). "In line with this, decreased insulin sensitivity and glucose intolerance were found in F2 generation." (PMID 30429829, 2018). "Although the A-K36M mice showed similar levels of glucose intolerance to Ctrl, they were more insulin resistant." (PMID 29728617, 2018).
Glucose intolerance (continued). "In conclusion, we found that administration of BQ-788 reduced the metabolic toll of IH exposure in mice, improving insulin sensitivity and limiting the development of glucose intolerance." (PMID 29896159, 2018). "The female offspring in the HF group had lower birth weights and glucose intolerance and higher serum insulin, triacylglycerol (TG) and total cholesterol (TC) levels at weaning compared with the Control group." (PMID 30233500, 2018). "The incidence of glucose intolerance increases with age owing to reduced insulin sensitivity and increased level of serum lipids." (PMID 30134873, 2018). "Endoplasmic reticulum (ER) stress contributes to impaired insulin signalling and whole-body glucose intolerance." (PMID 29720183, 2018). "Intriguingly, AE mice fed a HFD revealed higher β-cell responsiveness that was observed as excess in insulin levels, which compensates for glucose intolerance for at least 7 weeks." (PMID 29892281, 2018). "The first consequence of this murine Nnt deletion, described by Toye and coworkers in 2005, was glucose intolerance and reduced insulin secretion." (PMID 29046340, 2018). "It has been reported that the impaired glucose-stimulated insulin secretion (GSIS) in pancreatic beta cells is a major factor responsible for glucose intolerance in GK rats in which the beta cell mass is reduced by 60%." (PMID 30687391, 2018). "Glucose metabolism biomarkers included were C-peptide, glucose, insulin, intravenous glucose intolerance (Kg), and HOMA-IR." (PMID 30114269, 2018). "Remarkably, developmental blockade of VEGF-A signaling corrects islet hyper-vascularization in neonatal mice and rescues glucose intolerance and insulin secretion defects in adult Adrb2 mutant mice." (PMID 30303066, 2018). "The similar percentages obtained for these two assays indicate that there is an inversely proportional relationship between them, that is, the lower the insulin sensitivity, the greater the glucose intolerance." (PMID 30517288, 2018). "Removal of βlinc1 by knock-out (KO) in mice resulted in mild glucose intolerance, a lower number of insulin positive β-cells and a markedly increased amount of somatostatin positive δ-cells." (PMID 30551650, 2018). "The high incidence rate of glucose intolerance in Japanese populations is thought be connected with a low capacity for insulin secretion." (PMID 30425271, 2018). "An imbalance between insulin sensitivity and insulin secretion is the key pathophysiological mechanism in the progression of glucose intolerance." (PMID 29707577, 2018). "For that, mice were fed diets containing different amounts of fat during 6 months, which lead to different degrees of glucose intolerance and insulin resistance." (PMID 30670942, 2018). "Recently, T2DM patients treated with lobeglitazone not only improved their insulin sensitivity and glucose intolerance, but also showed an improvement in NASH." (PMID 30008738, 2018). "These mice exhibit a typical 20% increase in body weight, develop glucose intolerance with the concomitant increases in insulin and leptin levels and decreased adiponectin levels." (PMID 29449530, 2018). "Accordingly, antisense-treated mice exhibited impaired glucose intolerance, lower insulin content and fewer β-cells." (PMID 30551650, 2018). "Pancreas-specific deletion of Adrb2 results in glucose intolerance and impaired insulin secretion in mice, and unexpectedly, specifically in females." (PMID 30303066, 2018). "The polysaccharide-enriched fraction AAMP from Amillariella mellea fruiting body exerts an oral hypoglycemic effect at high dose by lowering fasting blood glucose, improving glucose-intolerance, and reducing serum insulin, TG, and FFA levels." (PMID 30583568, 2018). "GC in excess exerts diabetogenic actions that include the increase in plasma triacylglycerol and NEFA levels and the reduction in peripheral insulin sensitivity, accompanied by an increase in blood glucose levels and the presence of glucose intolerance." (PMID 30532777, 2018).
Glucose intolerance (continued). "While rosiglitazone is an effective insulin sensitizer, evidence suggests that rapamycin-induced glucose intolerance is mediated through increased hepatic gluconeogenesis." (PMID 29579736, 2018). "Diuretic drugs such as furosemide and hydrochlorothiazide induce glucose intolerance by the reduction of insulin-stimulated transport in adipose tissues and skeletal muscles." (PMID 29805204, 2018). "We used several methods to assess glucose intolerance and IR, including fasting insulin and glucose (HOMA-IR), IVGTT (AUC analyses), and CSI." (PMID 29682581, 2018). "OXT receptor-deficient mice exhibited increase β-cell death under metabolic stress conditions resulting in impaired insulin secretion and glucose intolerance under a high-fat diet." (PMID 29867762, 2018). "There are a number of studies in the literature in which fructose solutions, provided along with a chow diet, increase energy intake and body weight glucose intolerance, as well as plasma insulin and triglyceride levels." (PMID 30479649, 2018). "Our results demonstrate that changes in the immune cell composition of HFD-fed C57BL/6J mice affect the time course of glucose intolerance and insulin secretion." (PMID 29892281, 2018). "Conversely, c-Met knockout mice subjected to Ppx, had reduced β-cell mass, glucose intolerance, and decreased insulin secretion, when compared to wild type post-Ppx mice." (PMID 30214428, 2018). "Mice with global and skin-specific deletion (SKO) of SCD1 exhibit increased whole body energy expenditure and protection against diet-induced adiposity, hepatic steatosis, insulin sensitivity and glucose intolerance." (PMID 29965978, 2018). "The impaired glucose intolerance by DCM fraction further portrays an improved insulin secretion, sensitivity and β-cell function." (PMID 29449808, 2018). "The plasma glucose and insulin levels measured periodically during IVGTT were used to calculate AUCs as indexes of glucose intolerance and insulin secretion, respectively." (PMID 29744365, 2018). "Due to its action on peripheral insulin sensitivity, which is the primary mechanism responsible for glucose intolerance in CD, metformin represents the mainstay of antidiabetic treatment." (PMID 29915558, 2018). "For instance, knockdown of Irs1 in L6 rat and in primary human myotubes, showed impaired insulin-stimulated glucose uptake; similarly, liver specific Irs1 ablation leads to a marked glucose intolerance." (PMID 30469501, 2018). "GPR1 knockout mice fed with a high-fat diet developed serious glucose intolerance and a test of pyruvic acid tolerance suppressed glucose-stimulated insulin levels that consequently increased glycaemia." (PMID 30018639, 2018). "Sirt6 deficiency does not affect endocrine morphology, β-cell mass or insulin production but did result in glucose intolerance and defective glucose-stimulated insulin secretion in mice." (PMID 29535637, 2018). "Remarkably, L-Ago2 KO mice are resistant to S961-induced glucose intolerance after 1 week of treatment and S961 treatment of L-Ago2 KO mice resulted in a lower induction of plasma insulin levels and higher hepatic glycogen contents compared with control mice." (PMID 30201950, 2018). "Our study illustrates that olanzapine induces weight gain, fasting insulin elevation, glucose intolerance, and increase of TCF7L2 protein expression in liver, skeletal muscle, and adipose tissues of mice." (PMID 29713286, 2018). "Fasting serum glucose, serum insulin levels and glucose intolerance were all improved in ARA treated mice." (PMID 29342124, 2018). "The HF-diet even worsen the glycemic homeostasis leading to a significant increase in fasting blood glucose, insulin resistance and glucose intolerance when compared to the CT group (P < 0.05)." (PMID 30254287, 2018). "This study suggests that the presence of endogenous micronutrients in rapeseed oil promotes cellular adaptations to reverse glucose intolerance and improve the metabolism of insulin sensitive tissues." (PMID 29568317, 2018).